FAAH (fatty acid amide hydrolase)
Diseases named in the same sentence as FAAH in open-access papers (continued):
Sharing a sentence is not in itself a finding about the gene and the disease.
tumor (continued). "Importantly for the co-variance argument raised above, IL-4 also increases the expression of CB1 receptors in lymphocytes so we elected to focus on that molecule as a “test of concept” that a component of the tumour microenvironment can influence FAAH activity." (PMID 20808855, 2010). "Favourable cases, we noted, are marked by THRA-mediated metabolic regulation, RXRG-driven tumour suppression, GCGR-maintained metabolic homeostasis, and FAAH-mediated resolution of inflammation." (PMID 41007296, 2025). "For example, co-administration of the fatty acid amide hydrolase (FAAH) inhibitor URB597 with RSL3 enhances the ferroptosis-inducing activity of RSL3, leading to a substantial reduction in tumor volume in a nude mouse 786-O xenograft model." (PMID 41471274, 2025). "Patients with advanced RCC were divided into two groups (high vs. low expression) according to the median expression of FAAH and GPX4 in tumor tissue and then followed clinically." (PMID 37024452, 2023). "Here, we evaluated the anticancer property of the FAAH inhibitor URB597, investigating its potential to counteract epithelial-to-mesenchymal transition (EMT), a process crucially involved in tumor progression." (PMID 38139209, 2023). "This allowed the relationship between tumor grade and the expression of the enzymes to become more apparent, with a higher NAPE-PLD:FAAH ratio in higher tumor grades and thus more aggressive tumors." (PMID 31921630, 2019). "In line with this both high FAAH and low CNR1 in tumor tissue were seen in patients with lymphocytosis at diagnosis." (PMID 25594062, 2014). "In tumor tissue samples, seventy-one percent of the tumors had positive expression of GGH and FAAH simultaneously." (PMID 23374458, 2013). "Specifically, the supra-additive action of PEA and the FAAH inhibitor URB597 promotes cell death and delays in vivo tumor growth." (PMID 22429826, 2012). "Together, these results show that FAAH is not just a marker, but also a driver of a less aggressive, luminal-like tumor phenotype, and therefore it offers the potential to be studied as a candidate for differentiation therapy in patients with basal-like BC." (PMID 37253733, 2023). "In further support of this idea, FAAH immunostaining was absent from BC cells at the invasion front as well as in cells that had detached from the primary tumor, which constitute the most invasive (and therefore aggressive) subpopulation of BC cells." (PMID 37253733, 2023). "Although it is widely established that FAAH has diverse effects contributing to tumor progression, its effect on ferroptosis has not ever been explored." (PMID 37024452, 2023). "Conversely, after interference with FAAH, decreased FFA led to an insufficient substrate for the synthesis of LPA, which blocked the activation of COX-2/PGE2 signalling by HIF-1α and further inhibited the formation of tumours." (PMID 36702852, 2023). "Abnormally expressed FAAH in tumours could promote the hydrolysis of AEA, weaken the anti-tumour effect mediated by AEA, and enhance the hyperalgesia of patients with tumour." (PMID 36702852, 2023). "Indeed, a number of studies accordingly showed an inhibitory effect of blockers of the endocannabinoid-degrading enzymes fatty acid amide hydrolase (FAAH) and monoacylglycerol lipase (MAGL) on tumour development and spread." (PMID 34830856, 2021). "In non-malignant tissue, luminal FAAH immunoreactivity shows a lower intensity of staining than the tumour FAAH immunoreactivity, and neither non-malignant CB1 receptor immunoreactivity nor FAAH immunoreactivity is associated with disease severity or outcome." (PMID 32286386, 2020). "Additional CB receptor-independent pathways may also contribute: given the wide substrate specificity of FAAH and MAGL, increased expression will result in an increased production of long-chain fatty acids required to sustain tumour growth." (PMID 32286386, 2020).
tumor (continued). "The lack of change for Faah and Cnr1 in the TINT seen here is reminiscent of the situation in PCa patients, where tumour, but not TINT FAAH and CB1 receptor immunoreactivity is associated with disease severity and outcome." (PMID 32286386, 2020). "We subsequently discovered that the apparent discrepancy between the tissue levels and plasma concentrations of OEA in the sample patient cohort was due to a decrease in the expression of FAAH in the tumour, without any change in the expression of NAPE-PLD." (PMID 33375539, 2020). "By contrast, the role of FAAH in tumor cell spreading is marginally (invasion) or not at all (metastasis) defined." (PMID 26930716, 2016). "The expression levels of CNR1, CNR2 and FAAH did not correlate to the tumor cell content in the tissue as measured by flow cytometry." (PMID 25594062, 2014). "The discordant results detected between mRNA and protein expression of FAAH, PIR and TAF5L, could be due to multiple factors including, tumor heterogeneity, posttranscriptional regulation, differences in mRNA and protein turnover rates or poor specificity of the antibody used for IHC." (PMID 23374458, 2013). "In addition, possible reasons for the high level of FAAH-IR in the tumour tissue were not investigated by these authors." (PMID 20808855, 2010). "We also measured AEA, OEA and PEA amounts in the excised tumors by HPLC-MS, which showed that PEA, AEA and OEA levels were increased in tumor samples of mice treated with URB597 and co-treatment with RSL3 and URB597 but not RSL3 single treatment, which confirm the inhibition of FAAH." (PMID 37024452, 2023).
neurological disorders (15 papers, 2012 to 2025). "Such strategy has been already used for other neurological disorders with promising results and the fact that, in our study, FAAH enzyme experiences in FTD mice a reduction associated with trends of anandamide, PEA and OEA to be elevated, supports its pharmacological interest." (PMID 37149645, 2023). "So far, few FAAH inhibitors have been employed in clinical trials to treat diverse neurological disorders, all tested compounds are centrally active and covalently inactivate FAAH enzyme activity." (PMID 35743292, 2022). "Aggravation of the disease phenotype is also difficult to explain in view of the known anti-inflammatory and neuroprotective effects exerted by inhibition of FAAH activity in many animal models of neurological diseases." (PMID 34375644, 2021). "Fatty acid amide hydrolase (FAAH) has been recognized as a therapeutic target for several neurological diseases because its inhibition can exert neuroprotective and anti-inflammatory effects by boosting the endogenous levels of N-acylethanolamines." (PMID 31121907, 2019). "Although the molecular mechanisms activated by FAAH inhibition are still elusive, our study suggests that FAAH is a promising therapeutic target for various neurological disorders in which neuroinflammation plays a pivotal role." (PMID 31121907, 2019). "Rare genetic variants in the core endocannabinoid system genes CNR1, CNR2, DAGLA, MGLL and FAAH were identified in molecular testing data from 6,032 patients with a broad spectrum of neurological disorders." (PMID 29145497, 2017). "This is exemplified by the severe neurological disorder that occurred during a phase I trial of the fatty acid amide hydrolase (FAAH) inhibitor BIA 10-2474 and the psychiatric side effects associated with the cannabinoid receptor 1 (CB1) inverse agonist rimonabant." (PMID 39673602, 2025). "It should also be noted that rare genetic variations in ECS, including the genes CNR1 and CNR2 encoding CB1R and CB2R, respectively, as well as the genes for the degrading enzymes DAGLA, MGLL, and FAAH have been reported in patients with neurological disorders." (PMID 39796008, 2024). "In a previous medicinal chemistry program aiming at improving PF-3845 for the treatment of inflammatory pain and other nervous system disorders, the kinetic parameter kinact/Ki for covalent inhibition of human FAAH increased from 12,600 M−1s−1 (PF-3845) to 40,300 M−1s−1 (PF-004457845)." (PMID 33837735, 2021). "Also other FAAH inhibitors were found to be beneficial for the outcome of neurological diseases." (PMID 22457773, 2012). "The fatty acid amide hydrolase inhibitor, URB597, shows anti-oxidation characteristics in multiple neurological disorders." (PMID 38214766, 2024). "One of the primary degradative enzymes for endocannabinoids, fatty acid amide hydrolase (FAAH) attracted attention as a significant molecular target for developing new therapies for neuropsychiatric and neurological diseases, including chronic pain." (PMID 35056095, 2021). "Although controversies exist due to lack of sufficient observation on FAAH2 but FAAH seems to be a potential therapeutic intervention in neurological diseases and psychiatric disorders." (PMID 39796008, 2024). "Taken together, the regulation of expression levels of eCBs by targeting biological degrading molecules FAAH and MGL might serve as a potential and efficacious therapeutic target in neurological diseases." (PMID 39796008, 2024). "Regardless of the established cytotoxicity of lyso-sulfatide and the anti-inflammatory effects of FAAH inhibition seen in mouse models of several neurological diseases, genetic inactivation of FAAH did not mitigate, but rather exacerbated the disease phenotype of MLD mice." (PMID 34375644, 2021).
psychiatric disorder (10 papers, 2012 to 2026). A disorder characterized by behavioral and/or psychological abnormalities, often accompanied by physical symptoms. "Future research needs to establish what effect the FAAH rs324420 polymorphism has on the propensity to develop psychiatric disorders." (PMID 40564991, 2025). "Reduced FAAH expression could impact neuroinflammatory pathways, which are implicated in various psychiatric disorders." (PMID 39503008, 2024). "Main findings from human studies supporting the role of FAAH as a biomarker in psychiatric disorders." (PMID 32395111, 2020). "Herein, we discuss emerging insights, safety considerations, broader mechanistic implications, and future directions for FAAH-targeted therapeutics, advocating for a precision medicine approach to realise their potential in the treatment of psychiatric disorders." (PMID 42209468, 2026). "Conducting [11C]CURB PET experiments of FAAH density in these and other psychiatric disorders could help answer this question." (PMID 33462180, 2021).
neurodegenerative disease (8 papers, 2019 to 2024). A disorder of the central nervous system characterized by gradual and progressive loss of neural tissue and neurologic function. "Remarkably, our work contributes to the body of evidence that points to the selective inhibition of FAAH as a promising therapeutic strategy in neurodegenerative diseases." (PMID 34587978, 2021). "In this context, the effects of combining an allosteric positive modulator such as EC-21a or GAT229 with an inhibitor for FAAH or MAGL also deserve to be investigated for a comprehensive approach to the treatment of neurodegenerative diseases." (PMID 33302569, 2020). "Moreover, dual FAAH/cholinesterase inhibitors which might be beneficial for neurodegenerative diseases are currently under development." (PMID 34063947, 2021). "There is strong preclinical evidence that selective inhibitors of the main AEA-metabolizing enzyme, fatty acid amide hydrolase (FAAH), can ameliorate the unwanted effects in a variety of different laboratory animal models of neurodegenerative diseases." (PMID 31372820, 2019).
infection (6 papers, 2015 to 2023). The state of being infected such as from the introduction of a foreign agent such as serum, vaccine, antigenic substance or organism. "The FAAH was recently reported to be strictly related to defoliation, mediated by the infection of plants from Verticillium dahliae." (PMID 32785094, 2020). "Therefore, upregulation of FAAH genes may also increase cotton plant sensitivity to the ABA, disrupt hormone sensitivity, and predispose plants to pathogen infection accompanied by defoliation." (PMID 30609067, 2019).
central nervous system diseases (2 papers, 2023 to 2024). "Fatty acid amide hydrolase (FAAH), a membrane enzyme that terminates fatty acid amide-class signaling lipids, has seen the development of inhibitors for treating central nervous system diseases." (PMID 39194493, 2024).
inflammation (1 paper, 2014). Aberrant reaction of the microcirculation characterized by movement of fluid and leukocytes from the blood into extravascular tissues. "In summary, the potent and selective FAAH inhibitor URB597 was shown to have both anti-nociceptive and anti-inflammatory effects in the kaolin/carrageenan model of joint acute inflammation." (PMID 25260980, 2014).
intestinal disorder (1 paper, 2025). A non-neoplastic or neoplastic disorder that affects the small or large intestine. "Inhibitors of the FAAH enzyme, which degrade endocannabinoids, show therapeutic potential for use in hyperactivity intestinal disorders, providing benefits without psychotropic effects." (PMID 39941074, 2025).
metabolic disorder (1 paper, 2017). "Hence, one could speculate that transcriptional downregulation of endocannabinoid-degrading enzymes, possibly in response to later emerging metaflammation as shown for FAAH and TNFα, may represent a critical step in the development of hepatic alteration and metabolic disorder in obese subjects." (PMID 28859076, 2017).
FAAH also shares sentences with these, for which no sentence is quoted: inflammatory bowel disease (4 papers); Parkinson’s (4); Borderline personality disorder (3); cardiovascular disease (3); dementia (3); fibromyalgia (3); type 2 diabetes mellitus (3); acute lung injury (2); Alcohol (2); bipolar disorder (2); frontotemporal dementia (2); peripheral neuropathy (2); adenocarcinoma (1); Akinesia (1); astrocytoma (1); attention deficit-hyperactivity disorder (1); autism spectrum disorder (1); bacterial infection (1); basophilic leukaemia (1); binge eating disorder (1); blood vessel tumour (1); bulimia nervosa (1); cocaine addiction (1); colon adenocarcinoma (1); coronary artery disease (1); COVID-19 (1); Crohn disease (1); diabetic nephropathy (1); Dyskinesia (1); embryonic carcinoma (1).
A further 50 diseases each share a sentence with FAAH in 1 paper.